HSPA7 (heat shock protein family A (Hsp70) member 7 (pseudogene))
Synonyms: HSP70B
Gene: Transcribed unprocessed pseudogene on chromosome 1 (161,606,291 to 161,608,217, forward strand). Ensembl gene ENSG00000225217.
Diseases named in the same sentence as HSPA7 in open-access papers:
HSPA7 is named in the same sentence as 22 diseases in open-access papers, as found by Europe PMC text mining. Sharing a sentence is not in itself a finding about the gene and the disease. The quoted sentences say what the papers report.
glioblastoma (6 papers, 2021 to 2024). The most malignant astrocytic tumor (WHO grade IV). "As MES glioblastomas are strongly associated with higher immunosuppressive cell infiltration, we hypothesized that HSPA7 activated the immune microenvironment by promoting the phenotypic transformation of the GBM MES subtype." (PMID 34354698, 2021). "We also confirmed that HSPA7 enhanced the efficiency of anti-PD1 therapy utilizing GBM patient-derived glioblastoma organoids, an ex vivo model." (PMID 34354698, 2021). "The lncRNA HSPA7 is significantly overexpressed in glioblastoma (GBM) tissues, and m6A modification of HSPA7 promotes its expression." (PMID 37151887, 2023). "Another study found that m6A-regulated long non-coding RNA HSPA7 facilitated macrophage infiltration through the YAP1–LOX axis and enhanced the efficiency of anti-PD1 therapy in glioblastoma." (PMID 35936722, 2022). "We confirmed that HSPA7 promoted macrophage infiltration and SPP1 expression via upregulating the YAP1 and LOX expression of glioblastoma stem cells (GSCs) in vitro and in our clinical GBM tumor samples." (PMID 34354698, 2021). "HSPA7 was found to promote macrophage infiltration and SPP1 expression by upregulating YAP1 and LOX in glioblastoma stem cells (GSCs), both in vitro and in clinical GBM tumor samples." (PMID 39199429, 2024).
colon cancer (2 papers, 2021 to 2023). "Results showed that the expressions of HSPA1A and HSPA7 were downregulated in colon cancer cell lines." (PMID 34765552, 2021). "In summary, the increased expressions of HSPA1A1, HSPA1B, and HSPA7 were associated with poor prognosis, while that of HSPA9 was related to favorable prognosis for colon cancer patients." (PMID 34765552, 2021). "The expression difference of HSPA1A/HSPA1B/HSPA7/HSPA9 was verified in colon cancer cell lines and colonic epithelial cells." (PMID 34765552, 2021). "We found that increased expressions of HSPA1A1, HSPA1B, and HSPA7 were associated with poor prognosis, while that of HSPA9 was related to favorable prognosis for colon cancer patients." (PMID 34765552, 2021). "In conclusion, the increased expression of HSPA1A1, HSPA1B, and HSPA7 was associated with poor prognosis, and HSPA9 was related to favorable prognosis for colon cancer." (PMID 34765552, 2021). "Thus, the expression difference of HSPA7 between colon cancer tissues and normal tissues and the relationship of HSPA7 with survival in colon cancer need further clinical and experimental verification." (PMID 34765552, 2021). "HSPA7 may play roles in immune response and mitochondrial function in colon cancer." (PMID 34765552, 2021). "Univariate regression analysis was performed to explore the correlation of HSPA1A, HSPA1B, HSPA7, and HSPA9 expression with survival in colon cancer patients." (PMID 34765552, 2021). "To verify the expression difference of HSPA1A/HSA1B/HSPA7/HSPA9 in the TCGA database, we compared the expression of these genes in colon cancer cells (HCT116 and HT29) and colonic epithelial cells (CP-H040)." (PMID 34765552, 2021). "Colon cancer cell lines also showed increased expression of HSPA1B and HSPA9 and decreased expression of HSPA1A and HSPA7." (PMID 34765552, 2021). "Furthermore, GO ontology analysis was performed to screen the signaling pathways related to HSPA1A, HSPA1B, HSPA7, and HSPA9 in colon cancer." (PMID 34765552, 2021).
glial tumors (2 papers, 2021 to 2022). "To better map the association between WTAP and HSPA7, we explored the expression pattern in different grades of glioma in the TCGA, CGGA, Gravendeel and Rembrandt datasets." (PMID 34354698, 2021). "The expression of HSPA7 was highest in GBM (WHO IV) among the glioma specimens with three different WHO grades." (PMID 34354698, 2021). "For certain HSPs representatives (i.e., HSP10, HSPB1, DNAJC10, HSPA7, HSP90), a direct correlation between the protein level expression (based on IHC analysis) and poor overall survival prognosis for patients with glial tumors was identified." (PMID 36358853, 2022).
atherosclerosis (1 paper, 2021). A disease characterized by the build-up of fatty material and calcium deposition in the arterial wall resulting in partial or complete occlusion of the arterial lumen. "A long non-coding RNA (lncRNA) called HSPA7 promotes the development of atherosclerosis, plaque in arteries." (PMID 34857901, 2021). "Because we demonstrated that miR-223 was a target of HSPA7 in atherosclerotic lesions, miR-223 inhibition by HSPA7 might contribute to the progression of atherosclerosis." (PMID 34857901, 2021).
breast carcinoma (1 paper, 2014). "MCF10A cells exhibited significantly increased expression of HSP90AA1, CARHSP1, HSPA12A and decreased expression of HSPB1, HSPBL2, HSPA6, and HSPA7 (C vs H), while the three breast cancer lines showed no significant 2-fold or greater alterations in the expression of these genes (C’ vs H’)." (PMID 24511912, 2014).
colon adenocarcinoma (1 paper, 2021). "qRT-PCR validation results verified that HSPA2 was down-regulated in stomach adenocarcinoma and colon adenocarcinoma, HSPA7 and HSPA1A also were down-regulated in colon adenocarcinoma tissues." (PMID 34712697, 2021). "The mRNA expression level of HSPA7 was decreased in colon adenocarcinoma but increased in lung adenocarcinoma, kidney renal clear cell carcinoma and kidney renal papillary cell carcinoma." (PMID 34712697, 2021). "The qRT-PCR validation results in vivo showed that HSPA2 was down-regulated in stomach adenocarcinoma and colon adenocarcinoma; HSPA7 and HSPA1A also were down-regulated in colon adenocarcinoma." (PMID 34712697, 2021).
cytomegalovirus infection (1 paper, 2025). A herpesvirus infection caused by Cytomegalovirus. "One patient, with a preceding cytomegalovirus infection, was identified with three copies of parts of both FCGR3A and FCGR3B and three copies of the entire FCGR2C and HSPA7 genes, suggestive of a novel CNR (CNR5)." (PMID 40593358, 2025). "In the present study, we identified a unique case of a GBS patient with a preceding cytomegalovirus infection who had three copies of parts of FCGR3A and FCGR3B, along with three copies of the entire FCGR2C and HSPA7 genes." (PMID 40593358, 2025).
diabetics (1 paper, 2023). "In particular, beta cells of diabetics exhibited decreased expression of genes encoding molecular chaperones belonging to the heat shock families Hsp70 (HSPA1B, HSPA7, and HSPA8) and Hsp90 (HSP90AA1 and HSP90AB1) as well as co-chaperones (BAG3 and ST13) and nucleoporins (NDC1, NUP160, and POM121C)." (PMID 37569434, 2023).
melanoma (1 paper, 2021). A malignant, usually aggressive tumor composed of atypical, neoplastic melanocytes. "HSPA7 was found to be a risk factor in the cohort of melanoma patients who received anti-CTLA4 therapy but was found to be a beneficial prognostic factor in the TCGA SKCM cohort, exhibiting no obvious correlation with immune checkpoint expression or the immune response." (PMID 34354698, 2021). "We also confirmed the predictive value of HSPA7 in a cohort of melanoma patients who received anti-CTLA4 therapy and an IMvigor210 cohort of patients treated with anti-PD-L1 therapy." (PMID 34354698, 2021). "Thus, we used a cohort of melanoma patients who received anti-CTLA4 therapy and urothelial cancer cohorts of patients who received anti-PD-1 therapy (IMvigor210) to perform a complementary evaluation of the ability of HSPA7 to predict the immunotherapy response." (PMID 34354698, 2021).
pancreatic cancer (1 paper, 2022). "So far, two recent articles pointed out that the m6A-modified pseudogene HSPA7 could be a new immunotherapy target for GBM patients 34, and aberrant m6A modification of the pseudogene WTAPP1 results in increased translation of its protein-coding counterpart to promote pancreatic cancer progression." (PMID 36438489, 2022).
cancer (7 papers, 2020 to 2023). A tumor composed of atypical neoplastic, often pleomorphic cells that invade other tissues. "Statistically, HSPA7 is a risk factor in most cancers (such as ACC, LDBC, and CESC)." (PMID 34354698, 2021). "In the HSP70 family, HSPA7 was positively enriched in 19 cancer types, while HSPA14 was negatively enriched in 19 cancer types." (PMID 33225964, 2020). "We also explored the function of HSPA7 in various cancer types." (PMID 34354698, 2021). "HSPA7 expression was significantly positively correlated with the immune score and stromal score in all 33 cancer types." (PMID 34354698, 2021). "HSPA7 expression had prognostic significance in most cancers; in addition, it can regulate the expression of immune checkpoint genes and the activity of immune response pathways and was positively correlated with the immune score and stromal score in the majority of tumor types." (PMID 34354698, 2021). "However, little has been reported about the expression and role of HSPA7 in cancer." (PMID 34412642, 2021). "Moreover, HSPA7 was significantly positively correlated with immune checkpoint expression and the immune response in most cancer types such as GBM, LGG, OV, and LUAD." (PMID 34354698, 2021). "Collectively, these data emphasize that HSPA7 may be a key factor in facilitating the acquisition of various immunophenotypes in various cancers and may be considered in the development of more effective immunotherapies for GBM and other immunotherapy-resistant tumors." (PMID 34354698, 2021). "HSPA6 and HSPA7 are family members of the HSP70 proteins, which are abundantly present in cancer and play crucial roles in cancer development, progression, and metastasis, clinically resulting in diverse outcomes for patient survival." (PMID 36855205, 2023). "Equally, altered protein levels of FLNA, HSPA7, HGF, ERO1A, and GARS1, have been related to cancer migration, adhesion, poor patient prognosis, and metastasis." (PMID 35008958, 2022). "We find that the expression level of HSPA7 was significantly higher in KIRC tumor tissues (p = 6.183e−35) and in paired cancer tissues (p = 3.311e−18) compared with adjacent tissues." (PMID 34412642, 2021). "Pseudogenes played important roles in tumorigenesis, while there are nearly no reports about the expression and roles of HSPA7 in the cancer." (PMID 34412642, 2021). "We counted the numbers of pathways affected by each HSP; the results suggested that HSPA1L, HSPA12B, HSPA6, HSPA7 and HSPA12A may influence the activity of most cancer-related pathways and thus potently affect tumor development." (PMID 34712697, 2021).
tumor (3 papers, 2021 to 2023). "The HSPA7 expression levels was also correlated with tumor purity (cor = 0.125, p-value = 6.98e−03)." (PMID 34412642, 2021). "PD-L1 expression in immune cells (ICs) and tumor cells (TCs) was also assessed in the IMvigor210 cohort, and we examined the difference in HSPA7 expression among groups with different PD-L1 expression levels." (PMID 34354698, 2021). "The HSPA7 is highly expressed in KIRC tumor tissues, and its expression is related to clinico-pathological features and survival in KIRC patients." (PMID 34412642, 2021). "Then, the expression level of HSPA7 in KIRC tumor tissues and adjacent tissues were verified by GEPIA database, UALCAN database and qRT-PCR analysis." (PMID 34412642, 2021). "GSEA analysis displayed the high expression of HSPA7 in KIRC were related to several tumor- and immune-related pathways." (PMID 34412642, 2021). "GSEA analysis displayed the high expression of HSPA7 in KIRC were related to several tumor-related and immune-related pathways." (PMID 34412642, 2021). "First, we assessed the differences in HSPA7 expression between KIRC tumor tissues and adjacent tissues via differential expression scatter plots and paired difference analyses." (PMID 34412642, 2021). "The expression of HSPA7 in tumor tissues and GTEx normal brain tissues was determined in the GEPIA database." (PMID 34354698, 2021). "Our study showed that HSPA7 is very important in the tumor progression and may act as a poor prognostic biomarker for KIRC tumor by modulating immune infiltrating cells." (PMID 34412642, 2021). "Moreover, GSEA and Tumor Immunoassay Resource (TIMER) database were used to assay the potential mechanisms of HSPA7 in KIRC." (PMID 34412642, 2021). "The HSPA7-high expression group had significantly greater cell infiltration into the TME, higher immune and stromal scores, and lower tumor purity than the HSPA7-low expression group, confirming that HSPA7 could indeed regulate immune cell infiltration and immune-related gene expression." (PMID 34354698, 2021). "We implied that the expression level of HSPA7 was moderately positively associated with degree of macrophage, neutrophil, CD4+ T cells and DC infiltration, and weakly positively correlated with the degree of B cells and CD8+ T cells infiltration in KIRC tumor tissues." (PMID 34412642, 2021). "We used the single-sample gene-set enrichment analysis (ssGSEA) algorithm to investigate the difference in enriched tumor microenvironment (TME) infiltrating cells and the functional annotation of HSPA7 in individual GBM samples." (PMID 34354698, 2021). "Patients with higher PD-L1 expression levels in either immune cells or tumor cells exhibited higher HSPA7 expression levels (ANOVA summary IC: P = 0.0001, TC: P = 0.0009), indicating that HSPA7 can upregulate PD-L1 expression, suppressing immune activation." (PMID 34354698, 2021). "In summary, we explored that the pseudogenes HSPA7 is highly expressed in KIRC tumors and is correlated with tumor survival and progression." (PMID 34412642, 2021). "In summary, HSPA7 facilitated tumor promoting macrophage migration into the GBM TME by activating the YAP1–LOX axis, and our results indicated that HSPA7 might be a potential immunotherapy target for GBM patients." (PMID 34354698, 2021). "The immunofluorescent staining of our local clinical tumor tissue section analyses also showed that the expression of YAP1, LOX, CD68 (human macrophage marker), SPP1, and PD-L1 was enhanced in HSPA7-high GBM tissues compared to HSPA7-low tissues." (PMID 34354698, 2021).
HSPA7 also shares sentences with these, for which no sentence is quoted: mood disorder (2 papers); brain cancer (1); COVID-19 (1); gliomas (1); Hypertension (1); lung adenocarcinoma (1); Obesity (1); periodontitis (1); stomach adenocarcinoma (1); type 2 diabetes (1).